EDN2 (endothelin 2)
Description:
Endothelins are endothelium-derived vasoconstrictor peptides.
Synonyms: ET-2; PPET2; ET2
Tractability: Antibody: its Gene Ontology location is reachable by antibodies, with high confidence; UniProt places it where antibodies can reach, with medium confidence; UniProt predicts a signal peptide or a membrane-spanning region.
Gene: Protein-coding gene on chromosome 1 (41,478,774 to 41,484,686, reverse strand). Ensembl gene ENSG00000127129.
Subcellular location: Secreted
Subcellular location (Human Protein Atlas): Cytosol; Predicted to be secreted
Pathways (Reactome):
Signal Transduction: G alpha (q) signalling events; Peptide ligand-binding receptors
Gene Ontology:
Molecular function: endothelin B receptor binding; hormone activity
Biological process: artery smooth muscle contraction; cytokine-mediated signaling pathway; endothelin receptor signaling pathway; macrophage activation; macrophage chemotaxis; neutrophil chemotaxis; positive regulation of calcium-mediated signaling; positive regulation of cell population proliferation; positive regulation of heart rate; positive regulation of leukocyte chemotaxis; positive regulation of prostaglandin biosynthetic process; regulation of systemic arterial blood pressure by endothelin; vasoconstriction; vein smooth muscle contraction; cell surface receptor signaling pathway; hormonal regulation of the force of heart contraction; intracellular calcium ion homeostasis; positive regulation of smooth muscle contraction; positive regulation of the force of heart contraction by chemical signal; angiogenesis; axon extension; cell tip growth; endothelial cell migration; neuron projection development; regulation of vasoconstriction; and 1 more
Cellular component: extracellular region
Genetic constraint (gnomAD): Loss-of-function variants: 12 observed, 20.07 expected, observed/expected ratio (o/e) 0.6, 90% interval 0.38 to 0.97. The upper end of that interval is the gene's LOEUF score, 0.97, which puts it in group 4 of 6, group 1 being the genes least tolerant of losing a copy. Missense variants: 222 observed, 233.2 expected, observed/expected ratio (o/e) 0.95, 90% interval 0.85 to 1.06. Synonymous variants: 84 observed, 87.49 expected, observed/expected ratio (o/e) 0.96, 90% interval 0.8 to 1.15.
Homologues: Orthologues: chimpanzee EDN2 (99% identical), macaque EDN2 (96% identical), pig EDN2 (76% identical), guinea pig EDN2 (73% identical), rat Edn2 (69% identical), mouse Edn2 (69% identical), dog EDN2 (64% identical), rabbit EDN2 (42% identical), tropical clawed frog edn2 (34% identical), zebrafish edn2 (33% identical). Paralogues in human: EDN1 (32% identical), EDN3 (28% identical).